SERPINE2 (serpin family E member 2)
Diseases named in the same sentence as SERPINE2 in open-access papers (continued):
Sharing a sentence is not in itself a finding about the gene and the disease.
urothelial carcinoma (3 papers, 2021 to 2023). A malignant neoplasm derived from the transitional epithelium of the urinary tract (urinary bladder, ureter, urethra, or renal pelvis). "High expression of SERPINE2 indicates poor prognosis of urothelial carcinoma, which is consistent with the results of our study, and it also promotes tumorigenesis in various cancers." (PMID 37691944, 2023).
Alzheimer disease (2 papers, 2013 to 2021). A progressive, neurodegenerative disease characterized by loss of function and death of nerve cells in several areas of the brain leading to loss of cognitive function such as memory and language. "The VTA-predominant transcript SERPINE2 (Glia-derived nexin) is a serine protease inhibitor which can promote neurite extension by inhibiting thrombin, and which appears down-regulated in Alzheimer’s disease." (PMID 34305528, 2021).
Cirrhosis (2 papers, 2024 to 2025). A chronic disorder of the liver in which liver tissue becomes scarred and is partially replaced by regenerative nodules and fibrotic tissue resulting in loss of liver function. "Considering that COL1A2 is a collagen, we performed a correlation analysis between SOX4, LGALS3, SERPINE2, CD52, LPXN, and MPP6 and the progression of cirrhosis." (PMID 39194690, 2024).
colon adenocarcinoma (2 papers, 2023 to 2025). "This aligns with previous research indicating that Serpine2 expression is notably elevated in advanced colon adenocarcinoma tumors." (PMID 40642075, 2025). "SERPINE1 and SERPINE2 expression significantly increased in tumor advanced stage in colon adenocarcinoma (COAD)." (PMID 38274096, 2023).
fibrosis (2 papers, 2016 to 2025). the formation of excess fibrous connective tissue in an organ or tissue in a reparative or reactive process. "There results have demonstrated that for the first time the serpinE2/protease nexin-1was up-regulated in fibrosis model both in vivo and in vitro and the collagen content was significantly reduced by knockdown of serpinE2/protease nexin-1." (PMID 27876880, 2016). "Besides, SERPINE2 was promoted by the MEK1/2-ERK1/2 pathway via the transcription factors Elk1 during the cardiac fibrosis." (PMID 39754051, 2025).
lymph node metastasis (2 papers, 2022 to 2025). "Furthermore, GEPIA and ULCAN databases revealed a close association between high expression of SERPINE2 and clinical progression in COAD patients, indicating a correlation between increased levels of SERPINE2 and malignant progression as well as lymph node metastasis." (PMID 40463876, 2025).
prostate adenocarcinoma (2 papers, 2015 to 2023). "Malignant progression of SHH ligand-dependent tumors such as prostate adenocarcinomas would be inhibited by high Serpine2/PN-1, while the malignancy of SHH ligand-independent tumors such as medulloblastomas (this study) and gastric cancer would be aggravated." (PMID 25901736, 2015). "Likewise, LRP1-mediated internalization of SERPINE2/PN-1 inhibits SHH ligand-dependent signaling in human prostate adenocarcinoma cells, which results in down-regulation of SHH and GLI1 expression." (PMID 25901736, 2015). "Meanwhile, SERPINE2 was lower expressed in Bladder Urothelial Carcinoma (BLCA), KICH, Prostate adenocarcinoma (PRAD)." (PMID 38274096, 2023).
thyroid cancer (2 papers, 2017 to 2021). "However, the precise function of SERPINE2 in the genesis and progression of human thyroid cancers through upregulating cell division and proliferation still remains elusive." (PMID 28255192, 2017).
acute myeloid leukemia (1 paper, 2021). Acute myeloid leukemia (AML) is a group of neoplasms arising from precursor cells committed to the myeloid cell-line differentiation. "The YTHDF2 encoding gene was found to be overexpressed and responsible for development of acute myeloid leukemia (AML), whereas it turned into a tumor suppressor by targeting EGFR, IL11 and SERPINE2 mRNAs for degradation in hepatocellular carcinoma." (PMID 33658012, 2021).
ankylosing spondylitis (1 paper, 2024). An autoimmune chronic inflammatory disorder characterized by inflammation in the vertebral joints of the spine and sacroiliac joints. "The gene encoding Serpin Family E Member 2 (SERPINE2) has been implicated in disorders such as Visceral Heterotaxy and Ankylosing Spondylitis." (PMID 38383657, 2024).
atherosclerosis (1 paper, 2023). A disease characterized by the build-up of fatty material and calcium deposition in the arterial wall resulting in partial or complete occlusion of the arterial lumen. "SERPINE2 has been discovered to function in many vascular disorders, such as atherosclerosis and restenosis." (PMID 37537391, 2023).
benign tumors of the thyroid gland (1 paper, 2017). "Our findings indicate that the estimation of SERPINE2 and SLPI serum concentration may allow the preoperative differentiation of malignant and benign tumors of the thyroid gland." (PMID 28255192, 2017).
brain tumors (1 paper, 2015). "Our initial comparative analysis of the transcriptomes of human medulloblastomas and other brain tumors showed that SERPINE2/PN-1 is expressed at high levels in the WNT and SHH subgroups." (PMID 25901736, 2015).
breast disease (1 paper, 2023). "Besides, SERPINE2 is associated with respiratory or thoracic disease, integumentary system disease, endocrine system disease, and reproductive system or breast disease." (PMID 38274096, 2023).
chronic lung disease (1 paper, 2021). According to the definitions of the American and British Thoracic Societies, including pulmonary functional tests, X-rays, and CT scans for items such as fibrosis, bronchiectasis, bullae, emphysema, nodular or lymphomatous abnormalities. "Whilst SNPs in SERPINE2 have also been associated with COPD, the role of SERPINE2 in this chronic lung disease has not been determined." (PMID 34198546, 2021).
colorectal tumors (1 paper, 2010). "Furthermore, serpinE2 expression was also significantly enhanced in colorectal tumors, regardless of tumor stage and grade." (PMID 20942929, 2010).
diabetic neuropathy (1 paper, 2021). A chronic, pathological complication associated with diabetes mellitus, where nerve damages are incurred due to diabetic microvascular injury involving small blood vessels that supply these nerves, resulting in peripheral and/or autonomic nerve dysfunction. "miR-199a targeted SERPINE2 by binding to the 3′UTR of SERPINE2 and promoted coagulation resulting in the development of diabetic neuropathy." (PMID 35280258, 2021).
endometriosis (1 paper, 2025). The growth of functional endometrial tissue in anatomic sites outside the uterine body. "In a mouse model of endometriosis, SERPINE2 showed upregulated expression; its role in human endometriosis remains unstudied." (PMID 40698088, 2025).
endothelial dysfunction (1 paper, 2024). In vascular diseases, endothelial dysfunction is a systemic pathological state of the endothelium (the inner lining of blood vessels) and can be broadly defined as an imbalance between vasodilating and vasoconstricting substances produced by (or acting on) the endothelium. "This study, focusing on LSECs and the molecular bases of endothelial dysfunction during liver fibrosis from different mice models, found that SOX4, LGALS3, SERPINE2, CD52, and LPXN are potential key genes associated with endothelial dysfunction in liver fibrosis." (PMID 39194690, 2024). "This study identified key regulatory genes for endothelial dysfunction in liver fibrosis, namely SOX4, LGALS3, SERPINE2, CD52, and LPXN, which will provide new targets for the development of therapeutic strategies targeting endothelial dysfunction in LSECs and liver fibrosis." (PMID 39194690, 2024). "Moreover, we identified five key regulatory genes for endothelial dysfunction in liver fibrosis LSECs: SOX4, LGALS3, SERPINE2, CD52, and LPXN." (PMID 39194690, 2024). "Therefore, SOX4, LGALS3, SERPINE2, CD52, and LPXN may serve as key regulatory genes for endothelial dysfunction in liver fibrosis LSECs." (PMID 39194690, 2024).
hepatoblastoma (1 paper, 2022). Hepatoblastoma (HB) is a malignant hepatic tumor and is the most common pediatric liver cancer. "In this study, we examined SERPINE2 expression in hepatoblastoma and its association with clinicopathological features." (PMID 36505099, 2022). "Multivariate Cox analysis showed that tumor metastasis (HR: 3.84, P < 0.006), PRETEXT stage (HR: 4.57, P < 0.011), and SERPINE2 (HR: 4.71, P < 0.040) were the independent prognostic risk factors for hepatoblastoma." (PMID 36505099, 2022). "Univariate Cox analysis showed that vascular invasion (HR: 3.43, P = 0.012), tumor metastasis (HR: 6.72, P < 0.001), PRETEXT stage (HR: 7.46, P < 0.001), and SERPINE2 (HR: 7.36, P < 0.008) were the prognostic risk factors for hepatoblastoma." (PMID 36505099, 2022). "To confirm whether SERPINE2 is associated with the development of hepatoblastoma, we examined the expression level of SERPINE2 in hepatoblastoma tissues." (PMID 36505099, 2022). "The SERPINE2 mRNA expression levels were higher in hepatoblastoma tissues than in normal liver tissues in the GSE131329 dataset." (PMID 36505099, 2022). "SERPINE2 plays an important role in regulating extracellular matrix metabolism and is involved in the invasion, migration, and apoptosis of hepatoblastoma." (PMID 36505099, 2022). "In conclusion, we found that SERPINE2 was correlated with poor prognosis in hepatoblastoma." (PMID 36505099, 2022). "Moreover, our data indicated that elevated expression of SERPINE2 acts as an independent prognostic biomarker of poor overall survival (OS) in patients with hepatoblastoma." (PMID 36505099, 2022). "We used immunohistochemistry to detect SERPINE2 expression in 66 pairs of hepatoblastoma tumor tissues and matched nontumor liver tissues." (PMID 36505099, 2022). "In addition, we obtained the SERPINE2 mRNA expression from 9 pairs of hepatoblastoma tissues and matched nontumor liver tissues in our laboratory." (PMID 36505099, 2022).
Infertility (1 paper, 2025). "Our findings are consistent with a previous work that identified white blood cell genes linked to the infertile phenotype in heifers, with the SERPINE2 gene believed to play a role in heifer infertility." (PMID 40953057, 2025).
influenza (1 paper, 2025). An acute viral infection of the respiratory tract, occurring in isolated cases, in epidemics, or in pandemics; it is caused by serologically different strains of viruses (influenzaviruses) designated A, B, and C, has a 3-day incubation period, and usually lasts for 3 to 10 days. "Similarly, SERPINE2 correlated positively with TLR4 and RIG-I in COVID19 but negatively in influenza." (PMID 40825056, 2025).
liver cirrhosis (1 paper, 2024). "By analyzing the Co-DEGs associated with the progression and prognosis of liver cirrhosis, we identified five key genes: SOX4, LGALS3, SERPINE2, CD52, and LPXN." (PMID 39194690, 2024).
liver disease (1 paper, 2024). "SOX4, LGALS3, and SERPINE2 were strongly correlated with liver fibrosis grade and liver disease progression, with correlation coefficients (R) as high as 0.62 and 0.84 for SOX4 and 0.54 and 0.73 for LGALS3, respectively." (PMID 39194690, 2024).
liver fibrosis (1 paper, 2024). "Subsequently, we conducted qRT-PCR analysis to examine the expression of five key genes (SOX4, LGALS3, SERPINE2, CD52, and LPXN) in the liver tissues of mice with liver fibrosis." (PMID 39194690, 2024).
medulloblastoma (1 paper, 2015). A malignant, invasive embryonal neoplasm arising from the cerebellum. "Metadata analysis of microarray data from 437 human medulloblastoma samples establishes that SERPINE2/PN-1 is expressed by the vast majority of all medulloblastomas, with levels highest in the WNT and SHH subgroups." (PMID 25901736, 2015). "This potential role of Serpine2/PN-1 during medulloblastoma development in Ptch1Δ/+ mice was assessed genetically by inactivating one or both copies of the Serpine2/Pn-1 gene using a constitutive loss-of-function (Pn-1Δ) allele." (PMID 25901736, 2015). "SERPINE2/PN-1 is expressed in most human medulloblastomas, with levels being highest in the two subgroups with altered WNT and SHH pathway activities." (PMID 25901736, 2015). "Transcriptome analysis of human medulloblastomas shows that SERPINE2, also called Protease Nexin-1 (PN-1) is overexpressed in most medulloblastomas, in particular in the SHH and WNT subgroups." (PMID 25901736, 2015). "The genetic and molecular analysis analyses of mouse medulloblastomas in Ptch1Δ/+ and Ptch1Δ/+Pn-1Δ/+ mice reveals that aberrant expression of Serpine2/Pn-1 promotes proliferation and facilitates progression of PNLs to medulloblastomas." (PMID 25901736, 2015). "siRNA-mediated downregulation of SERPINE2/PN-1 in human DAOY medulloblastoma cells reduced their proliferation." (PMID 25901736, 2015). "To gain further insight into the potential involvement of Serpine2/PN-1 in medulloblastoma development, we took advantage of Ptch1 heterozygous (Ptch1Δ/+) mice." (PMID 25901736, 2015). "In summary, our analysis shows that Serpine2/PN-1 boosts malignant progression of PNLs to medulloblastomas, in which the Hedgehog pathway is activated in a SHH ligand-independent manner." (PMID 25901736, 2015). "This genetic analysis in mice shows that Serpine2/PN-1 is required for proliferation of PNL cells and malignant progression to medulloblastomas in the context of SHH ligand-independent up-regulation of Hedgehog pathway activity." (PMID 25901736, 2015).
Oedemas (1 paper, 2005). "Oedemas frequently accompanies the preeclamptic condition, therefore specific malfunctions of SERPINE2 and SERPING1 could represent risk factors for placental diseases." (PMID 16129025, 2005).
preeclampsia (1 paper, 2025). Preeclampsia is a hypertensive disorder of pregnancy that is characterized by new-onset hypertension with proteinuria presenting after 20 weeks of gestation, and depending on mild or severe forms may initially present with severe headache, visual disturbances, and hyperreflexia. "Our findings suggest that decreased levels of circulating SERPINE2 cause increased risk of preeclampsia." (PMID 40991151, 2025). "We also identified two circulating proteins (encoded by SERPINE2 and SIGLEC6) as potentially causal for preeclampsia." (PMID 40991151, 2025). "Decreased levels of SERPINE2 and SIGLEC6 were potentially causal for increased risk of preeclampsia." (PMID 40991151, 2025). "Analyses suggested that decreased levels of circulating proteins encoded by SERPINE2 and SIGLEC6 were causal for increased risk of preeclampsia." (PMID 40991151, 2025).
pulmonary disorders (1 paper, 2011). "We examined further the role of SERPINE2 polymorphisms in the development of pulmonary disorders, and report here a significant association between SERPINE2 SNPs and panlobular emphysema." (PMID 22145704, 2011).
scleroderma (1 paper, 2023). Scleroderma is a rare autoimmune connective tissue disorder characterized by abnormal hardening of the skin and, sometimes, other organs. "Additionally, a variety of other genes associated with inflammatory as well as malignant diseases were enriched in scleroderma fibroblasts (POSTN, PRSS23, TNC, and SERPINE2)." (PMID 37443817, 2023).
squamous carcinoma (1 paper, 2023). "High expression of Serpine2 has been connected to increased cellular migration and proliferation in squamous carcinoma, and it has also been suggested as a cancer-promoting factor that increases angiogenesis." (PMID 36717781, 2023).
Thromboembolism (1 paper, 2022). The formation of a blood clot inside a blood vessel that subsequently travels through the blood stream from the site where it formed to another location in the body, generally leading to vascular occlusion at the distant site. "This implies that SERPINE2 could be considered an attractive drug target for prevention of COPD, IPF, and thromboembolism." (PMID 36388766, 2022).
tumor (76 papers, 2010 to 2026). "We discovered an association between SERPINE2 and macrophage infiltration, as well as a interaction between SERPINE2 and the tumor-associated macrophages." (PMID 40463876, 2025). "For example, circRNA cSERPINE2, derived from the tumor gene SERPINE2, shuttles into tumor-associated macrophages." (PMID 40034598, 2025). "More importantly, many of the downregulated genes (Fn1, Hspb1, Postn, Mia, Fgfr1, Serpine2) have been associated with tumor metastasis." (PMID 39287984, 2024). "Several studies have shown that SERPINE2 expression is associated with tumorigenesis and tumor cell invasion." (PMID 38274096, 2023). "Previous studies have shown that SERPINE2 expression is associated with tumorigenesis and tumor cell invasion." (PMID 36646679, 2023). "SERPINE2, a serine or cysteine proteinase inhibitor, is widely implicated in tumorigenesis and tumor progression." (PMID 36011368, 2022). "Previous studies have shown that SERPINE2 is closely associated with tumor cell apoptosis and malignant transformation." (PMID 36505099, 2022). "Upregulated genes included cartilage-associated genes (COMP, MATN3, and COL11A2), collagen- and extracellular matrix-associated genes (COL9A2, SFRP2, and SERPINE2), and tumor metastasis- and progression-associated genes (SLC38A3, FST, ITGA11, and DGKI)." (PMID 36192442, 2022). "In accordance with the tumor phenotypes mostly associated with VM, Serpine2 and Slpi were significantly more expressed in HER2+, TNBC (basal) and claudin-low tumors of relapsing patients." (PMID 34359928, 2021). "Proteases and their inhibitors play important roles in ECM remodeling, prompting us to examine the impact of serpinE2 loss on the tumor ECM." (PMID 27793045, 2016). "Here, we speculate that the SERPINE2 derived from cancer cells may stimulate tumor-associated macrophages to secrete TGF-β, leading to malignant transformation of tumors, as indicated by our previous enrichment analysis results." (PMID 40463876, 2025). "Additionally, Tissue chips, Transwell assays, Cell counting kit-8 assay, and co-culture system were used to evaluate the relationship between SERPINE2 and polarization of tumor-associated macrophages." (PMID 40463876, 2025). "SERPINE2 may also play an important role in activating and rousing immune cells, which is significantly associated with tumor treatment response." (PMID 37174750, 2023). "MG from tumor bearing animals show also upregulation of Timp2, Serpine2, Cst7, and Ctsd, genes encoding proteases or their modulators participating in reorganization of extracellular matrix, which may reflect invasion supporting properties." (PMID 33608526, 2021). "We show here that targeting serpinE2 via KD or by treatment with the antibody causes a reduction in the population of tumor-promoting macrophages, as well as a decrease in chemokine ligand 2 (CCL2), which is known to stimulate macrophage abundance and polarization." (PMID 27793045, 2016). "Multi-layered evidence demonstrates that SERPINE2 integrates tumor-intrinsic signaling and microenvironmental remodeling." (PMID 42099617, 2026). "This post-translational modification enhanced SERPINE2 protein stability, and SERPINE2 overexpression effectively reversed the tumor-suppressive effects induced by KAT2A silencing." (PMID 41968399, 2026). "These dual tumor-intrinsic and stromal functions position SERPINE2 as a molecular hub in post-metastatic adaptation." (PMID 42099617, 2026). "Patients with Fn+ metastatic had higher levels of Serpine2 mRNA expression in their tumor samples compared to matching normal tissues." (PMID 40642075, 2025). "Western blotting suggested that the protein level of Serpine2 gene was increased in tumor tissues of Fn+ patients." (PMID 40642075, 2025). "The results showed that compared with normal tissues, the expression of SERPINE2 protein was significantly upregulated in COAD tumor tissues, consistent with its high mRNA levels." (PMID 40463876, 2025).